CD4 (CD4 molecule)
Diseases named in the same sentence as CD4 in open-access papers (continued):
Sharing a sentence is not in itself a finding about the gene and the disease.
AIDS (continued). "The frequency of opportunistic infections in HIV/AIDS patients increases as the CD3+CD4+ lymphocyte count decreases." (PMID 30998710, 2019). "HIV-1 infection is a chronic infection that induces a steady decrease in CD4+ T lymphocytes and leads to acquired immunodeficiency syndrome (AIDS)." (PMID 30811489, 2019). "In AIDS patients, severely decreased CD4 cell counts and long-term anti-CMV therapy resulted in upwards of 20% incidence of resistance to all anti-CMV medications by 9 to 12 months in one study." (PMID 31905656, 2019). "Assessment of the fitted models shows that viral load monitoring is a better predictor of HIV/AIDS progression than CD4 cell count." (PMID 30770728, 2019). "In conclusion, it is shown that low levels of CD4+ T lymphocytes in patients newly diagnosed with HIV/AIDS are found in the Yunnan province." (PMID 30998710, 2019). "When CD4+ cell counts drop to below 200 cells/μL immunological AIDS develops and is often indication to start ART." (PMID 31447765, 2019). "Despite that most HIV-infected individuals experience progressive CD4+ T cell loss and develop AIDS, a minority of HIV-infected individuals remain asymptomatic and maintain high level CD4+ T cell counts several years after seroconversion." (PMID 30665429, 2019). "Of these, 555 had CD4+ cell count < 200 cells/mm3 and 82 presented with an AIDS-defining illness, although they had CD4+ cell count > 200 cells/mm3." (PMID 31080478, 2019). "On initial workup, hewas screened and diagnosed with AIDS; CD4 count was less than 20 cells/μL (1%) andRNA-PCR (polymerase chain reaction) 191 000 copies/mL." (PMID 31423835, 2019). "as a common feature in HIV/AIDS patients, especially when the CD4+ T cell counts fall below 200cells/μL." (PMID 32546916, 2019). "In humans, it is widely known that HIV/AIDS patients with low CD4 counts have a high risk of developing disseminated MAC, indicating the importance of CD4 T cells in NTM immunity." (PMID 30837992, 2019). "While activated CMV is typically controlled by robust virus-specific CD4+ and CD8+ T-cell responses, under various forms of immunosuppression, including HIV/AIDS, CMV replicates and spreads rapidly to nearby tissue causing a variety of diseases." (PMID 31905656, 2019). "Histoplasmosis and cryptococcosis are systemic fungal diseases frequently encountered in immunocompromised hosts, particularly in patients with HIV/AIDS with low CD4 counts." (PMID 31316875, 2019). "These well-studied secondary infections in AIDS indicate that CD4+ T cell-mediated control of latent microbes—including Toxoplasma gondii and Treponema pallidum in the CNS—is critical for our health." (PMID 31396143, 2019). "Even though this proportion is alarming, when compared to the study results from the period 1999–200434, with baseline median CD4 count of 276 cells/μL and 34% persons presenting with clinical AIDS, our data show that the situation has improved." (PMID 31754119, 2019). "The study was conducted to assess the pattern of malaria parasitaemia densities in different levels of CD4 T-cells among people living with HIV/AIDS in the surrounding areas within 10 km radius of the site." (PMID 31354844, 2019). "A likelihood ratio test was also performed to compare HIV/AIDS progression based on CD4 cell count monitoring with progression based on viral load monitoring." (PMID 30770728, 2019). "It is noteworthy that, after CD4 counting, adherence to antiretroviral therapy is the second largest predictor of progression to AIDS and death." (PMID 30916226, 2019). "Human immunodeficiency virus (HIV) patients especially patients with acquired immunodeficiency syndrome (AIDS) have a compromised immune system (low CD4 counts) and as such, they are 3-times more likely to be infected with HPVs." (PMID 31600915, 2019). "It was previously reported that the mean number of CD4+ T cells in newly diagnosed HIV/AIDS patients in China in 2010 was 334 ± 302 cells/μl." (PMID 30998710, 2019).
AIDS (continued). "In the meantime, in some countries, including Italy, up to 29% of the patients arrive late at a HIV diagnosis, with CD4+ T-cell (CD4+) count <200/mmc or with an AIDS-defining condition (infection and/or cancer) already present at the moment of diagnosis." (PMID 30931978, 2019). "Statistical analyses showed that, after cART, CD4 cell counts in asymptomatic patients were significantly higher compared to AIDS‐KS patients in both screening and validation." (PMID 30549196, 2019). "Typically, when a patient with AIDS associated KS adheres to antiretroviral therapy (ART), their CD4 cell count is elevated and clinical presentation of KS tumors either stabilize or resolve." (PMID 31404285, 2019). "Advanced stages of HIV/AIDS indicated by reduced levels of CD4+ count in patients reported in this study, showed a corresponding elevated markers of hepatotoxicity." (PMID 31339937, 2019). "Subsequently, CD4 count was <20cells/μL with AIDS-defining illness already present at the time of presentation toour facility." (PMID 31423835, 2019). "Patients who were initiated on ART at an advanced stage of HIV/AIDS (baseline CD4 lymphocyte count ≤50 cells/mm3) were four times more likely to experience first-line ART failure (AOR = 3.8, 95% CI: 1.5–9.6) in this study." (PMID 31215397, 2019). "This again confirms that viral load monitoring is a better marker of HIV/AIDS progression than CD4 cell count." (PMID 30770728, 2019). "In AIDS, CD4+ T cell subsets recognizing each microbial species are equally vulnerable to depletion." (PMID 31396143, 2019). "The primary endpoint was clinical failure at three years, defined as death, new AIDS‐defining event, or CD4 count <50 cells/mm3." (PMID 30897303, 2019). "In the next subsection prevalence plots for the two Markov models, one in which CD4 count is used as a marker of HIV/AIDS progression and the other one in which viral load count is used as the marker of the disease progression, are compared." (PMID 30770728, 2019). "Patients initiating abacavir in the post-screening period were also more likely to be ART-naïve, have lower HIV viral loads, have higher CD4 cell counts and less likely to have a history of AIDS defining illness at baseline." (PMID 30651100, 2019). "We verified the validity of the syllogism: as HIV-tropism (CRT) contributes to the onset of non-AIDS events which are successfully predicted by the CD4/CD8 ratio and VACS index, then CRT correlates with these two variables." (PMID 30818365, 2019). "To end the HIV/AIDS epidemic, we require strategic information, which includes CD4 cell counts, to make informed clinical decisions and effectively monitor key surveillance indicators." (PMID 30892272, 2019). "In the TDs group, almost half of patients were females (n = 59, 48%), 67 subjects (54.5%) showed a CD4+ lymphocytes nadir <200/mm3 and 71.54% (n = 88) experienced a previous AIDS-defining event." (PMID 31857648, 2019). "The authors found that approximately 60% of PLHIV were severely immunosuppressed, i.e., had AIDS symptoms or CD4+ cell count < 200 cells/mm3 when they started ART." (PMID 31080478, 2019). "Approximately 30% of T. gondii seropositive AIDS patients with a CD4+ T cell count below 200/μl develop a reactivated TE, which is lethal if not treated adequately with anti-parasitic drugs." (PMID 30873157, 2019). "This study has revealed that low levels of CD4+ T cells can be observed in newly-diagnosed HIV/AIDS patients in the Yunnan province." (PMID 30998710, 2019). "Undeniably, anemia is the most important clinical problem seen in people living with HIV/AIDS; its severity increases as CD4 count declines and with progression of the disease HIV/AIDS to advanced stage." (PMID 30941180, 2019). "The mean CD4 count at HIV diagnosis was 551 cells/μL ± 225.1; 20 (40%) patients had a CD4 cell count < 500 cells/μL and 2 (4%) patients had a diagnosis of AIDS by CD4 criteria (< 200 cells/μL and/or CD4% < 14%)." (PMID 31783911, 2019).
AIDS (continued). "This contradicts with findings from previous studies that CD4 cell count is a better predictor for HIV/AIDS progression than HIV RNA." (PMID 30770728, 2019). "Since this study was performed before the publication of the START study advocating for early ART initiation, ART initiation was deferred until the occurrence of the following; HIV-related disease, AIDS defining illness, pregnancy and CD4 count< 350 cells/μl." (PMID 31438877, 2019). "Although this approach demonstrated the potential for CAR-T cells in ALCL, ongoing CD4 depletion could lead to a T cell immunodeficiency similar to that observed in the acquired immunodeficiency syndrome (AIDS) induced by the human immunodeficiency virus (HIV)." (PMID 31058076, 2019). "Meanwhile, in a study by the British Columbia Centre for Excellence in HIV/AIDS which investigated treatment outcomes among those who initiated cART at high CD4 cell count, 80% of study participants were male." (PMID 31882645, 2019). "Prior to 1997, only those with AIDS diagnoses are reported and consequently, the highest reporting rates are found in those with low CD4 counts of <200 cells/μL (1.11yr−1, 95% Cr I 0.89–1.51 for men in 1996 and 1.06yr−1, 95% Cr I 0.89–1.38 for women)." (PMID 30772250, 2019). "In general, on one hand, the prognosis is related to the extension of the disease, extranodal involvement, LDH concentration, bone marrow involvement, age, number of CD4 lymphocytes in peripheral blood, functional status, and previous diagnosis of AIDS." (PMID 31543075, 2019). "The study included 161 patients from 15 hospitals with median age of 49 years; 29.3% had previous AIDS stage and median CD4+ lymphocyte nadir of 170 cells/uL." (PMID 30819101, 2019). "As systemic immune activation is considered the driving force of CD4+ T cell depletion and development of acquired immunodeficiency syndrome (AIDS), it is important to understand the link between epithelial gut damage and systemic immune activation in PLWH." (PMID 30967860, 2019). "Tg mice expressing entire coding sequences of HIV-1 (CD4/HIVWT) or HIV-1 Nef alone (CD4C/HIVNef) under the control of a CD4 promoter in HIV-1 target cells showed human AIDS-like symptoms." (PMID 30871179, 2019). "Subjects with even an optimal CD4 T cell recovery but a persistent elevation and expansion of CD8 T cells still have an increased immune activation and a higher risk of non-AIDS morbidity and mortality." (PMID 30818365, 2019). "Human immunodeficiency virus (HIV) infection remains incurable, and depletion of immune cells (especially CD4+ T helper cells) is the hallmark of HIV infection, leading to acquired immunodeficiency syndrome (AIDS) and side effects." (PMID 31406672, 2019). "Overall, the results show that although both CD4 cell count and viral load are the surrogate markers of HIV progression, viral load is more powerful in monitoring progression of HIV/AIDS in patients on antiretroviral therapy than CD4 cell count." (PMID 30770728, 2019). "In untreated patients, the infection progresses to acquired immunodeficiency syndrome (AIDS) – as characterized by a decline in CD4+ T-cells." (PMID 31208472, 2019). "Low CD4 count or late presentation always leads to low ART uptake and late HIV care, resulting in serious damage to the immune system in HIV/AIDS, this is inevitably linked to higher mortality." (PMID 30742626, 2019). "We also observed that patients on a 2‐DR were more likely to have diagnoses of comorbid conditions, a lower CD4 count, and a history of AIDS compared to patients taking 3‐DRs." (PMID 31802641, 2019). "Patients initiating a 2‐DR (n = 1337, 13%) were older, and more likely to have a lower CD4 count, a history of AIDS and comorbid conditions than patients initiating a 3‐DR." (PMID 31802641, 2019). "CD4 count is a key indicator for AIDS disease progression, and understanding its behavior over time is critical for monitoring HIV+ patients." (PMID 30450612, 2019).
AIDS (continued). "The one-year CD4+ cell count after HAART initiation is a preferable predictor of immune reconstitution in HIV/AIDS patients with sustained viral suppression." (PMID 31455209, 2019). "In 2009, 55.4% of new cases presented with either CD4 counts of <200 cells/mm3 or clinical AIDS, compared to 40.0% in 2016." (PMID 31347260, 2019). "Stage of HIV/AIDS, CD4+ count, ART adherence, and hemoglobin level has also been reported as risk factors for opportunistic parasitic infections." (PMID 32546916, 2019). "Results from the analysis show that viral load monitoring predicts deaths of HIV/AIDS patients better than CD4 cell count monitoring." (PMID 30770728, 2019). "Low CD4 count predicted hrHPV persistence, while prior AIDS predicted ≥HSIL, which supports continued focus on previously and currently immunocompromised WLWH with respect to screening for HPV-related cancers." (PMID 31438877, 2019). "Late initiation of ART was defined as CD4+ cell count < 200 cells/mm3 or presence of AIDS-defining illness." (PMID 31080478, 2019). "While age-based targeting greatly reduces the number of deaths over the long-term, it comes at the cost of slightly more AIDS deaths relative to CD4-based targeting in the years immediately following the TasP campaign." (PMID 31846456, 2019). "This study assesses the use of both viral load (HIV RNA) and CD4 cell count in the monitoring of HIV/AIDS progression." (PMID 30770728, 2019). "This VitD deficiency has been related to high plasma viral load, increased inflammation and immune activation, decreased CD4+ T-cells, and rapid AIDS progression; whereas higher levels of VitD seem to provide natural resistance to HIV infection." (PMID 31640710, 2019). "42% of patients had CD4 greater than 500, 60% of patients had undetectable viral load and 11% were in AIDS stage at the time of entering the Peruvian health system." (PMID 30941891, 2019). "High levels of VitD seem to provide a natural resistance to HIV infection, whereas low levels of VitD are related to a higher values of HIV viral load in plasma, inflammation, immune activation, decrease of CD4+ T-cells and rapid AIDS progression." (PMID 30841566, 2019). "Some studies show that CD4 cell count monitoring is the best for predicting HIV/AIDS progression and other studies show that viral load monitoring is the best predictor." (PMID 30770728, 2019). "Since 2011, the World Health Organization (WHO) has recommended screening for cryptococcal antigen (CrAg) in people living with HIV/AIDS (PLHAs) with a CD4 count <100 cells/μl." (PMID 31344140, 2019). "The prevalence of cryptococcal antigenaemia ranges from 6% to 11.7% among low CD4 T-cell count or among HIV/AIDS patients." (PMID 31771096, 2019). "To assess the impact of APOL1 HR on disease progression in untreated individuals from date of seroconversion to CD4 <200 cell/mm3 and to incident AIDS, we performed time-to-event analysis for 227 African American seroincident participants." (PMID 30733721, 2019). "Many types of microfluidic point-of-care (POC) devices have been developed for monitoring HIV/AIDS by counting CD4 cells." (PMID 30875995, 2019). "Generally, this study showed the concept that AIDS is the sum total of laboratory diagnosis plus an opportunistic infection or a CD4 count of below 200/μL." (PMID 30281631, 2018). "The incidence rates of non-AIDS composite events were significantly different between the cutoffs for CD4/CD8 ratio, with 11.42 per 100 PYS (95% CI 7.45–17.52) for current CD4/CD8 ratio < 0.3 and 2.23 per 100 PYS (1.77–2.81) for ratio > 0.45." (PMID 30261902, 2018). "Persistent immune activation is a striking consequence of HIV-1 infection and a driving force of CD4+ T cell depletion and AIDS events during chronic infection." (PMID 29636753, 2018). "This study further suggested that TCM interventions were significantly more effective than placebo for reducing plasma viral load and increasing CD4+ T lymphocyte count in patients with AIDS." (PMID 29757986, 2018).
AIDS (continued). "Consistently, The Adult AIDS Clinical Trials Group (ACTG) interruption treatment trail found that higher baseline CD4+ T cell immune activation predicted the delay of viral rebound following treatment interruption." (PMID 29636753, 2018). "The final phase is AIDS, which is highly symptomatic as the CD4 is reduced to less than 200 cells/mm3." (PMID 30344234, 2018). "Most of the HIV/AIDS patients on antiretroviral therapy were died in a short period due to tuberculosis comorbidity, began with lower amount of CD4, being underweight, merchant, and being on WHO clinical stage IV." (PMID 30359289, 2018). "The median CD4+ cell count of the population was 463 cells/mm3, and 58% had a documented AIDS diagnosis." (PMID 29293632, 2018). "Low CD4/CD8 ratios despite effective ART are associated with continuous immune dysregulation, immune senescence and are predictive of non-AIDS morbidity and mortality." (PMID 29739341, 2018). "Different definitions have been adopted to indicate the LP of HIV, such as “a CD4 cell count of < 350 cells/μL or AIDS-defining event at the first follow-up ” or “a CD4 cell count of < 200 cells/μL or an AIDS-defining event within 3 months of HIV diagnosis ”." (PMID 29720151, 2018). "In adults with horizontally acquired HIV infection, an inverted CD4:CD8 ratio is associated with persistent immune activation, size of HIV reservoir and predicts an increased risk of non‐AIDS‐defining adverse events." (PMID 30084150, 2018). "The mean sojourn times revealed that patients take longer time in the AIDS defining states (CD4 cell count below 200) before they move to the other states." (PMID 29343268, 2018). "According to the Diagnostic Criteria for HIV/AIDS (WS 293–2008), an HIV-positive patient with clinical manifestation or/and CD4 <200 cells/mm3 is defined as having HIV/AIDS." (PMID 30110373, 2018). "Visitect CD4 (Omega Diagnostics, Alva, UK), a rapid disposable semi quantitative CD4 test, was launched in Washington D.C. at the 2012 AIDS conference and was developed by the Burnet Institute in collaboration with Omega Diagnostics Group." (PMID 30344234, 2018). "The initial focus of ART scale-up was to reduce severe morbidity and mortality; patients with an AIDS-defining condition or a CD4+ T-lymphocyte (CD4) count <200 cells/μL were therefore considered eligible for ART." (PMID 29514233, 2018). "In HIV-AIDS patients the decrease in the pool of CD4+ T cells and consequent diminution of the CD4/CD8 ratio, produced by HIV infection provokes a generalized immune depression." (PMID 29971054, 2018). "The CD4/CD8 ratio predicts the time to AIDS in HIV-1-infected untreated individuals, and a low CD4/CD8 ratio (0.51–0.80) is associated with an increased risk of losing virological control in HIC individuals." (PMID 30050532, 2018). "C. neoformans primarily infects individuals with a low CD4+ T cell count, particularly patients with AIDS; C. gattii is more likely to infect immunocompetent individuals." (PMID 29463005, 2018). "HIV variants that use the CXCR4 co‐receptor were associated with more than 10 years of diagnosis, with older individuals, in the AIDS stage, with low CD4 counts and higher viral load levels (p < 0.05)." (PMID 29671462, 2018). "HIV/AIDS disease progression was assessed by measuring CD4+ cell count and viral load of the patients, and GST polymorphism was determined by amplifying the GSTT1 and GSTM1 genes using multiplex PCR, with CYP1A1 gene as an internal control." (PMID 29795558, 2018). "Progression for AIDS in HIV-1 positive patients is mainly characterized by CD4+ T cell depletion, specifically Th1 and Th17 cells, which impact negatively on immune protection against different opportunistic pathogens." (PMID 30481211, 2018). "Systemic chronic immune activation is considered as the driving force of CD4+ T-cell depletion and AIDS." (PMID 30034377, 2018).